FGFBP1 (fibroblast growth factor binding protein 1)
Description:
Acts as a carrier protein that release fibroblast-binding factors (FGFs) from the extracellular matrix (EM) storage and thus enhance the mitogenic activity of FGFs. Enhances FGF2 signaling during tissue repair, angiogenesis and in tumor growth.
Synonyms: FGF-BP; FGF-BP1; FGFBP-1; HBp17; FGFBP
Tractability: Antibody: UniProt places it where antibodies can reach, with high confidence; its Gene Ontology location is reachable by antibodies, with high confidence; UniProt predicts a signal peptide or a membrane-spanning region.
Gene: Protein-coding gene on chromosome 4 (15,934,507 to 15,939,171, reverse strand). Ensembl gene ENSG00000137440.
Subcellular location: Secreted, extracellular space; Cell membrane
Pathways (Reactome):
Signal Transduction: FGFR2b ligand binding and activation
Gene Ontology:
Molecular function: protein binding; growth factor binding; heparin binding; fibroblast growth factor binding
Biological process: positive regulation of blood vessel endothelial cell proliferation involved in sprouting angiogenesis; positive regulation of cell migration involved in sprouting angiogenesis; cell-cell signaling; negative regulation of cell population proliferation; signal transduction
Cellular component: plasma membrane; extracellular region; cell surface
Genetic constraint (gnomAD): Loss-of-function variants: 12 observed, 15.12 expected, observed/expected ratio (o/e) 0.79, 90% interval 0.51 to 1.29. The upper end of that interval is the gene's LOEUF score, 1.29, which puts it in group 5 of 6, group 1 being the genes least tolerant of losing a copy. Missense variants: 312 observed, 282.57 expected, observed/expected ratio (o/e) 1.1, 90% interval 1.01 to 1.21. Synonymous variants: 113 observed, 107.82 expected, observed/expected ratio (o/e) 1.05, 90% interval 0.9 to 1.23.
Homologues: Orthologues: chimpanzee FGFBP1 (99% identical), macaque FGFBP1 (94% identical), mouse Fgfbp1 (63% identical), rat Fgfbp1 (60% identical), dog FGFBP1 (59% identical), pig FGFBP1 (59% identical), rabbit FGFBP1 (57% identical), guinea pig FGFBP1 (53% identical), tropical clawed frog fgfbp1 (31% identical). Paralogues in human: FGFBP3 (19% identical), FGFBP2 (18% identical).
Diseases named in the same sentence as FGFBP1 in open-access papers:
FGFBP1 is named in the same sentence as 53 diseases in open-access papers, as found by Europe PMC text mining. Sharing a sentence is not in itself a finding about the gene and the disease. The quoted sentences say what the papers report.
breast cancer (18 papers, 2014 to 2025). A primary or metastatic malignant neoplasm involving the breast. "The expression of this research shows that FGFBP1 from patients with esophageal is a high expression (70.2%), thus making the results consistent with the expression of colon cancer, pancreatic cancer, and breast cancer." (PMID 33381388, 2020). "The present study aimed to analyze the differential expression of genes related to growth factors such as FGF2, FGFBP1, TGFA, TGFBR3, and IGF1R in a radiation- and estrogen-induced experimental breast cancer model." (PMID 36430763, 2022). "STAT3 bound to the 5′ region of the FGFBP1 gene in a human lung cancer cell line (NCI-H358) and breast cancer cells (HCC70 and T47D)." (PMID 34341336, 2021). "Furthermore, the results suggest that all these markers should be used in the earlier stages of the disease, since an analysis of BRCA patients indicated that the FGF2, FGFBP1, TGFA, TGFBR3, and IGF1R gene expression levels were present in late stages 3 and 4 of breast cancer." (PMID 36430763, 2022). "Nevertheless, no changes were detected in the expression of the FGFBP1 gene and protein levels in leukemic (HEL) and breast cancer (MDA-MB-468) cells, suggesting that B4 specifically acts on lymphoma, unlike in other cancer cells." (PMID 39005939, 2024).
pancreatic cancer (8 papers, 2020 to 2025). "Equally importantly, FGFBP1 can promote hepatocellular carcinoma metastasis, and patients with pancreatic cancer who express higher FGFBP1 levels have been shown to have a worse prognosis." (PMID 36979151, 2023). "The expression levels of FGFBP1 in normal pancreatic epithelial cells (HPNE cells) and pancreatic tumor cells (PANC-1 cells) were examined, we found that FGFBP1 expression was higher in PANC-1 cells than in HPNE cells." (PMID 37575248, 2023). "FGFBP1 increases proliferation and invasion and promotes EMT in pancreatic cancer." (PMID 40509555, 2025). "It was observed that fibroblast growth factor (FGF) binding protein 1 (FGFBP1) plays a pivotal role in the proliferation and metastasis of pancreatic cancer cells and negatively correlates with the survival of patients with pancreatic cancer." (PMID 34978469, 2022).
colon carcinoma (6 papers, 2011 to 2024). "Studies have shown that the knockdown of FGFBP1 can induce apoptosis in colon carcinoma cells mediated through caspase-3/9 activation and alterations in mitochondrial metabolism upon FGFBP1 knockdown." (PMID 39005939, 2024).
epidermoid carcinoma (6 papers, 2011 to 2024). "Heparin-binding protein 17 (HBp17), first purified in 1991 from the conditioned medium of the human A431 squamous cell carcinoma (SCC) cell line, was later renamed fibroblast growth factor-binding protein 1 (FGFBP-1)." (PMID 38713345, 2024). "In a recent study, the same group of researchers noted that ED-71 inhibited the growth of squamous cell carcinoma (SCC) cells in vitro and in vivo by down-regulating the expression of HBp17/FGFBP-1, a factor that enhances angiogenesis as well as promotes tumour growth, and FGF-2." (PMID 37299554, 2023). "FGFBP1 was firstly found in human epidermoid carcinoma A431 cells, acting as a noncovalent carrier for FGF-1 or FGF-2." (PMID 31058187, 2019).
oral squamous cell carcinoma (5 papers, 2020 to 2024). "Other studies have also shown that calcitriol can inhibit the growth of oral squamous cell carcinoma cells by blocking the HBp17/FGFBP-1 signalling cascades on the mRNA and protein levels, which are crucial in cancer angiogenesis." (PMID 37299554, 2023). "This review will discuss the effect of vitamin D3 on the expression of HBp17/FGFBP-1 in oral squamous cell carcinoma (OSCC) and whether it can be further related to the prevention and treatment for OSCC." (PMID 38713345, 2024). "Previous study indicated that ED-71 could suppress oral squamous cell carcinoma by inhibiting HBp17/FGFBP-1, FGF-2, CD31, Ki-67, and Cyp24A1." (PMID 33336024, 2020). "A previous study reported that 1-α,25-dihydroxyvitamin D3 (1α,25(OH)2D3) inhibits HBp17/FGFBP-1 expression in SCC and oral squamous cell carcinoma (OSCC) cell lines via the nuclear factor-kappa B (NF-κB) signaling pathway." (PMID 34072393, 2021).
asthma (4 papers, 2017 to 2024). "Poly-L-arginine has been shown to stimulate angiogenesis in asthma by inducing the expression of Fibroblast Growth Factor Binding Protein 1 (FGFBP1) in epithelial cells." (PMID 39830981, 2024). "Elevated FGFBP1 expression was also detected in asthma clinical samples, as well as in ovalbumin (OVA)-induced chronic asthma mouse models." (PMID 34341336, 2021). "We next analyzed the correlation between FGFBP1 concentration and eosinophil count in patients with asthma and controls, respectively." (PMID 34341336, 2021). "Taken together, these data indicated that FGFBP1 was higher in patients with asthma than in controls, and its concentration in asthmatic peripheral blood was closely related to the activated eosinophils." (PMID 34341336, 2021). "The results showed that FGFBP1 expression in patients with asthma was strongly correlated with eosinophil count (r = 0.722, P = 0.002)." (PMID 34341336, 2021). "An altered epithelial repair response was observed across both airways in severe asthma, evident by the increased expression of cytokeratin genes such as FGFBP1." (PMID 28045928, 2017). "Thus, it is likely that activated STAT3 is involved in asthma, at least partly, by regulating transcriptional activation of FGFBP1." (PMID 34341336, 2021). "Rapamycin, an inhibitor of mTORC1, could dramatically lead to the downregulation of FGFBP1 expression and significantly reduced the number of neovascularizations in asthma models." (PMID 34341336, 2021). "Given that PLA is widely used to mimic MBP in vitro and PLA-induced FGFBP1 expression in airway epithelial cells, we speculated that FGFBP1 is overexpressed in patients with asthma." (PMID 34341336, 2021). "Moreover, an altered epithelial repair response (e.g. FGFBP1) was evident across both airway sites reflecting a significant aspect of disease in severe asthma unadressed by current therapies." (PMID 28045928, 2017). "Thus, it is likely that FGFBP1 is a potential therapeutic target of airway remodeling in asthma." (PMID 34341336, 2021). "We also detected a positive correlation between FGFBP1 expression and p-STAT3 activity in OVA-induced asthma mouse models." (PMID 34341336, 2021). "The mice with asthma consistently exhibited higher levels of p-S6, p-STAT3, and FGFBP1 protein than in the control group." (PMID 34341336, 2021). "In the current study, based on the analysis of human airway epithelial cells and OVA-induced asthma mouse models, we demonstrated that STAT3 serves as a downstream effector of mTORC1 and transcriptionally upregulates FGFBP1 through directly binding to its promoter and enhancing its transcription." (PMID 34341336, 2021). "In the current research, we reanalyzed our RNA-seq data and found that fibroblast growth factor-binding protein 1 (FGFBP1), a proangiogenesis factor, was significantly elevated in PLA-treated airway epithelial cell lines, asthma clinical specimens, and ovalbumin (OVA)-induced chronic asthma model." (PMID 34341336, 2021). "Moreover, we found elevated FGFBP1 expression in asthma clinical specimens and an OVA-induced animal model of asthma." (PMID 34341336, 2021). "Therefore, we analyzed the FGFBP1 concentration in peripheral blood samples from 28 participants (13 with asthma and 15 healthy controls without asthma) using ELISA." (PMID 34341336, 2021).
bladder cancer (4 papers, 2021 to 2024). "So, FGFBP1 is generally considered an indicator of early stages of pancreatic and colorectal adenocarcinoma, and as a biomarker it is very useful in predicting bacillus Calmette–Guérin response in bladder cancer." (PMID 36979151, 2023). "Among the main repressed genes in bladder cancer, there are fatty acid binding protein 4 (FABP4) and fibroblast growth factor binding protein 1 (HBP17), RGS4, tissue inhibitor of metalloproteinase 3 (TIMP3), WNT5b, URB, and collagen type VIII, alpha 1 (COL8A1)." (PMID 34835969, 2021). "PVRL4 was predominantly expressed in BC epithelial cells, AREG was expressed in BC epithelial cells and normal control myeloid cells, and FGFBP1 and WFDC2 were expressed in bladder cancer epithelial cells but not in normal tissue." (PMID 38532419, 2024).
Hypertension (4 papers, 2017 to 2025). The presence of chronic increased pressure in the systemic arterial system. "We were able to identify and validate miR-4432 as a fundamental modulator of FGFBP1 and we demonstrated that miR-4432 significantly reduces mitochondrial oxidative stress, a well-established pathophysiological hallmark of hypertension." (PMID 36979151, 2023). "Pathway analysis shows an association between FGFBP1 and hypertension." (PMID 40357364, 2025). "This combined treatment approach led to a reduction in FGFBP1 levels, offering a potential strategy for managing hypertension in the context of lymphoma treatment." (PMID 39005939, 2024). "The experimental observation herein reported indicates that miR-4432 targets FGFBP1 in human ECs, representing a novel potential strategy against numerous diseases characterized by endothelial dysfunction, including hypertension." (PMID 36979151, 2023). "Preclinical studies in spontaneously hypertensive rats substantiated a contribution of the FGFBP1 genomic locus to hypertension and to glomerular damage." (PMID 36979151, 2023). "However, when a combination of B4 was administered with CC, a hypertension treatment drug, there was a reversal in the expression of FGFBP1." (PMID 39005939, 2024). "Patients with hypertension often exhibit high levels of FGFBP1 as a pathology marker." (PMID 39005939, 2024). "Consistent with our results, hypertensive patients have been shown to have approximately 1.5- and 1.4-fold higher expression of FGFBP1 mRNA and protein compared to normotensive subjects, further corroborating the crucial role of FGFBP1 in the pathophysiology of hypertension." (PMID 36979151, 2023). "In addition, the induction of FGFBP1 in a transgenic mouse model resulted in sustained hypertension and increased vascular sensitivity to the vasoconstrictor angiotensin II (Ang II) via ROS and MAP kinase pathway signaling." (PMID 36979151, 2023). "Taken together, our results indicate for the first time, to the best of our knowledge, that miR-4432 specifically targets the 3′UTR of FGFBP1, thereby representing a novel potential strategy against hypertension, cerebrovascular disease, and other disorders characterized by endothelial dysfunction." (PMID 36979151, 2023).
oral cancer (4 papers, 2020 to 2023). "A vitamin D analog, eldecalcitol (ED-71)-induced exosomal miR-6887-5p, suppresses oral cancer cell proliferation by targeting the 3′-UTR of heparin-binding protein 17/fibroblast growth-factor-binding protein-1 (HBp17/FGFBP-1)." (PMID 36612314, 2023). "In the normal adult tissues, some studies have shown that FGFBP1 has also been shown to induce tumorigenic potential in epithelial cells and to be highly expressed in oral cancer cell lines and tissues." (PMID 33381388, 2020). "In oral cancer, the increase of miR-100 inhibited FGFBP1 and FGFR3, which over-expressed in radio-resistant cells, indirectly corroborate our hypothesis." (PMID 35477450, 2022). "Heparin-binding protein 17/fibroblast growth factor-binding protein-1 (HBp17/FGFBP-1) has been observed to induce the tumorigenic potential of epithelial cells and is highly expressed in oral cancer cell lines and tissues." (PMID 34072393, 2021).
lung carcinoma (3 papers, 2018 to 2023). "FGFBP1 and ST6GALN2 proteins were found to be weakly expressed in lung cancers irrespective of tumor type." (PMID 30473748, 2018).
prostate carcinoma (3 papers, 2009 to 2021). A carcinoma that arises from epithelial cells of the prostate gland. "By performing a screen for proteins in pre-operative and post-operative serum from men with high-risk prostate cancer, we identified CASP8, MSLN, FGFBP1, ICOSLG, TIE2, and S100A4 proteins as candidate biomarkers for high-risk prostate cancer." (PMID 33828176, 2021). "MSLN, FGFBP1, ICOSLG, and TIE2 were also elevated in sera from patients with BPH, suggesting that MSLN, FGFBP1, ICOSLG, and TIE2 were not specific for high-risk prostate cancer." (PMID 33828176, 2021).
epithelial dysplasia (2 papers, 2021 to 2024). "The expression of HBp17/FGFBP-1 is observed in epithelial cells, and its expression increased with the severity of epithelial dysplasia." (PMID 34072393, 2021).
esophageal squamous cell carcinoma (2 papers, 2020 to 2023). Esophageal squamous cell carcinoma (ESCC) is a type of esophageal carcinoma (EC) that can affect any part of the esophagus, but is usually located in the upper or middle third. "We can speculate that FGFBP1 may promote the development of esophageal squamous cell carcinoma through FGF2." (PMID 33381388, 2020). "In this study, the immunohistochemistry of FGF2, FGFR3, and FGFBP1 was used to further verify the expression of the three proteins in 172 patients with esophageal squamous cell carcinoma (ESCC) who had not received preoperative chemoradiotherapy and its effect on the prognosis of ESCC." (PMID 33381388, 2020).
pancreatic adenocarcinoma (2 papers, 2021 to 2025). "Currently, a hydrogel developed for the effective release of fibroblast growth factor-binding protein 1 (FGFBP1) inhibitors to treat pancreatic adenocarcinoma is in progress at CNR Nanotec Lecce." (PMID 40868153, 2025). "In addition, c-Myc has been shown to promote proliferation and metastasis through directly binding to the promoter of FGFBP1 and enhancing its transcription in pancreatic adenocarcinoma." (PMID 34341336, 2021).
actinic keratosis (1 paper, 2020). A precancerous lesion of the skin composed of atypical keratinocytes. "And other studies have found that overexpression of FGFBP1 can lead to skin diseases, such as psoriasis, actinic keratosis, and squamous cell carcinoma of the skin." (PMID 33381388, 2020).
breast-invasive carcinoma (1 paper, 2022). "The correlation between EGFR expression and FGF2 and FGFBP1 gene expression levels in breast invasive carcinoma subtypes with purity adjustment was statistically significant in its positive correlation in all BRCA, except for BRCA-Her2." (PMID 36430763, 2022).
cervical squamous cell carcinoma (1 paper, 2021). A squamous cell carcinoma arising from the cervical epithelium. "In addition, ERK and p38 MAPK activation has been suggested to be involved in the upregulation of FGFBP1 in the cervical squamous cell carcinoma cell line ME-180." (PMID 34341336, 2021).
endothelial dysfunction (1 paper, 2023). In vascular diseases, endothelial dysfunction is a systemic pathological state of the endothelium (the inner lining of blood vessels) and can be broadly defined as an imbalance between vasodilating and vasoconstricting substances produced by (or acting on) the endothelium. "Fibroblast growth factor binding protein 1 (FGFBP1) has been associated with endothelial dysfunction at the level of the blood–brain barrier (BBB)." (PMID 36979151, 2023).
invasive carcinoma (1 paper, 2022). A carcinoma that is not confined to the epithelium, and has spread to the surrounding stroma. "TIMER2.0 was used to identify the correlation between EGFR and other gene expressions in breast-invasive carcinoma subtypes with purity adjustments such as FGF2, FGFBP1, TGFA, TGFBR3, and IGF1R in all BRCA patients." (PMID 36430763, 2022).
liver cancer (1 paper, 2022). An epithelial or non-epithelial malignant neoplasm that arises from the liver. "Although FGFBP1 expression in tumor cells is critical for the development of pancreatic, colon, and liver cancers, the molecular mechanisms by which FGFBP1 promotes the activation of HSCs remain unclear." (PMID 35951441, 2022).